ZNF317 (zinc finger protein 317)
Description:
May function as a transcription factor. May play an important role in erythroid maturation and lymphoid proliferation.
Tractability: PROTAC: ubiquitination databases record sites on it.
Gene: Protein-coding gene on chromosome 19 (9,140,380 to 9,163,424, forward strand). Ensembl gene ENSG00000130803.
Subcellular location: Nucleus
Subcellular location (Human Protein Atlas): Nucleoplasm
Pathways (Reactome):
Gene expression (Transcription): Generic Transcription Pathway; Regulation of endogenous retroelements by KRAB-ZFP proteins
Gene Ontology:
Molecular function: protein binding; DNA-binding transcription factor activity, RNA polymerase II-specific; RNA polymerase II cis-regulatory region sequence-specific DNA binding
Biological process: regulation of transcription by RNA polymerase II; regulation of DNA-templated transcription
Cellular component: nucleoplasm; nucleus
Genetic constraint (gnomAD): Loss-of-function variants: 13 observed, 21.03 expected, observed/expected ratio (o/e) 0.62, 90% interval 0.4 to 0.98. The upper end of that interval is the gene's LOEUF score, 0.98, which puts it in group 4 of 6, group 1 being the genes least tolerant of losing a copy. Missense variants: 646 observed, 798.56 expected, observed/expected ratio (o/e) 0.81, 90% interval 0.76 to 0.86. Synonymous variants: 303 observed, 318.04 expected, observed/expected ratio (o/e) 0.95, 90% interval 0.87 to 1.05.
Homologues: Orthologues: chimpanzee ZNF317 (99% identical), macaque ZNF317 (97% identical), rabbit ZNF317 (92% identical), dog ZNF317 (90% identical), pig ZNF317 (89% identical), guinea pig ZNF317 (86% identical), mouse Zfp317 (83% identical), rat Zfp317 (83% identical). Paralogues in human: ZNF546 (42% identical), ZNF658 (40% identical), ZNF568 (40% identical), ZNF699 (40% identical), ZNF573 (40% identical), ZFP14 (39% identical), ZNF585B (39% identical), ZNF571 (39% identical), ZNF606 (39% identical), ZNF841 (39% identical), ZNF41 (39% identical), ZNF33B (39% identical), and 164 more.
Diseases named in the same sentence as ZNF317 in open-access papers:
ZNF317 is named in the same sentence as 2 diseases in open-access papers, as found by Europe PMC text mining. Sharing a sentence is not in itself a finding about the gene and the disease. The quoted sentences say what the papers report.
cancer (1 paper, 2025). A tumor composed of atypical neoplastic, often pleomorphic cells that invade other tissues. "Two genes encoding zinc finger proteins, ZFX (X-linked) and ZNF317 (autosomal), also had a higher female sex-bias on the pan-cancer level (q-value = 2.9×10−3 and 0.065; effect size = 0.13 and 0.09)." (PMID 39975298, 2025).
ZNF317 also shares sentences with these, for which no sentence is quoted: cervical cancer (1 paper).